SMYD3 (SET and MYND domain containing 3)
Diseases named in the same sentence as SMYD3 in open-access papers (continued):
Sharing a sentence is not in itself a finding about the gene and the disease.
hepatocellular carcinoma (continued). "Treatment with Smyd3-ASOs suppressed liver tumor growth in a mouse model of chemical-induced hepatocellular carcinoma and inhibited the tumor growth rate, migration, and capacity by blocking cellular dedifferentiation and the expansion of hepatic cancer stem cells." (PMID 39482529, 2024). "The findings that SMYD3 is significantly upregulated in most colorectal carcinomas, hepatocellular carcinomas, and breast cell carcinomas support a model in which its aberrant expression modifies established patterns of gene expression, ultimately driving unrestrained proliferation." (PMID 35076487, 2021). "SMYD3 is a lysine methyltransferase that regulates the expression of over 80 genes and is required for the uncontrolled proliferation of most breast, colorectal, and hepatocellular carcinomas." (PMID 33333978, 2020). "Pharmacologically targeting SMYD3 with BCI-121 inhibitor represses hepatocellular carcinoma cells." (PMID 32516941, 2020). "In addition, SET and MYND Domain-Containing Protein 3 (SMYD3) knockdown in colorectal carcinoma and hepatocellular carcinoma cells was found to diminish the occupancy of c-Myc at hTERT promoter via reduction in H3K4 trimethylation and histone H3 acetylation." (PMID 27548225, 2016). "Furthermore, SMYD3 binds and activates the Snail family transcriptional repressor 2 (SNAI2) promoter, leading to increased levels of H3K4me3, H3K9Ac, and H3K14Ac; thus, the coexpression of SMYD3 and ANKDH1 is associated with poor prognosis in hepatocellular carcinoma patients." (PMID 39482529, 2024). "In addition, SMYD3 plays an important role in tumorigenesis, including in colorectal cancer, hepatocellular carcinoma, breast cancer, gastric carcinoma, cervical cancer, prostate cancer, pancreatic cancer, lung cancer, ovarian cancer, esophageal cancer, bladder cancer, and malignant glioma." (PMID 36575438, 2022). "However, it was also reported that miR-597 could suppress HCC cell proliferation dependent on SMYD3 in hepatocellular carcinoma." (PMID 34458365, 2021). "The upregulated SMYD3 is found to promote the expression of ZEB1, Snail, and MMP9 to induce EMT via interacting with SMAD2/3, resulting in the sorafenib resistance of hepatocellular carcinoma." (PMID 39092293, 2024). "In particular, the interaction between SMYD3 and AMPK was confirmed in multiple gastrointestinal cancer cell lines (CRC, GC, hepatocellular carcinoma, pancreatic cancer), confirming the role of SMYD3 in the metabolism of gastrointestinal cancer." (PMID 36496998, 2022). "SMYD3 interacts with the RNA helicase HELZ, forming a complex with RNA polymerase II and promoting cancer cell proliferation in colorectal and hepatocellular carcinomas." (PMID 34201935, 2021). "Most recently, overexpressed SMYD3 enhanced MMP2 and CDK2 expression in hepatocellular carcinoma and upregulated Bcl-2, Bcl-xl, MMP-2, and MMP-9 in NSCLC to facilitate tumorigenicity and cancer progression." (PMID 34201935, 2021). "Recently, it has been seen that SMYD3 binds to CDK2 and MMP2 promoter, increasing gene transcription I hepatocellular carcinoma." (PMID 32516941, 2020). "By knocking down SMYD3 with siRNA, there was a significant reduction in hTERT mRNA in colorectal carcinoma HCT116 cells, hepatocellular carcinoma Hep3B cells, and Hodgkin’s lymphoma L1236 cells." (PMID 27242892, 2016). "SMYD3 complexed with RNA polymerase II and bound 5′-CCCTCC-3′ and 5′-GGAGGG-3′ motifs in the promoter region to transcriptionally activate downstream genes, like Nkx2.8 in colorectal and hepatocellular carcinomas." (PMID 37237385, 2023).
colorectal cancer (25 papers, 2006 to 2026). A primary or metastatic malignant neoplasm that affects the colon or rectum. "To define the functional contribution of SMYD3 to colorectal cancer (CRC) progression, we combined genetic loss-of-function, pharmacologic inhibition, and gain-of-function approaches in SW480 and HCT116 cells." (PMID 41301830, 2025). "The overexpression of SMYD3 later in life has been associated with a range of cancers, including breast, lung, and colorectal carcinomas." (PMID 35076487, 2021). "Here, we performed an extensive in vitro and in vivo molecular and functional characterization, revealing the pivotal role of the lysine methyltransferase SET and MYND Domain Containing 3 (SMYD3) in colorectal cancer stem cell (CRC-SC) biology." (PMID 40588481, 2025). "Pan-cancer expression analysis using GEPIA2, which integrates RNA-seq data from TCGA and GTEx, revealed that SMYD3 mRNA is widely expressed across solid tumors and notably upregulated in several malignancies, including colorectal cancer (CRC)." (PMID 41301830, 2025). "Taken together, the genetic (knockdown/overexpression), pharmacologic (BCI-121), and chromatin (ChIP) evidence demonstrate that CDCP1 is a direct chromatin target of SMYD3 in colorectal cancer cells." (PMID 41301830, 2025). "In colorectal cancer, SMYD3 affects proliferation in vitro, and silencing SMYD3 suppresses tumor growth in xenograft-bearing mice." (PMID 39482529, 2024). "Previous studies reported that DNA methylation levels are dysregulated in most cancers, and the methylation level in the SMYD3 promoter region is low in colorectal cancer." (PMID 37237385, 2023). "The expression and activity of SMYD3 was first reported in a preclinical model of colorectal cancer (CRC) in which SMYD3 was strongly upregulated throughout tumorigenesis at both the mRNA and protein level." (PMID 36838987, 2023). "The methylation level of SMYD3 promoter is significantly lower in colorectal cancer tissues than in adjacent normal tissues." (PMID 36816359, 2023). "The disease pathway for diethylnitrosamine (DEN)-induced hepatocellular and colorectal carcinomas involves damage to DNA and subsequent cell death, both of which are reduced in SMYD3-KO mice." (PMID 36838987, 2023). "SMYD3 has been highly correlated, most notably with breast, hepatocellular, and colorectal carcinomas as well as with lung and pancreatic ductal adenocarcinomas." (PMID 36838987, 2023). "We conclude that Inhibitor-4 is a promising inhibitor of SMYD3 and SMYD3-mediated breast, lung, and colorectal cancers." (PMID 35076487, 2021). "For instance, SMYD3 is known to be upregulated in colorectal cancers." (PMID 38892284, 2024). "The DLD-1 colorectal cancer cell line has been shown to express lower levels of SMYD3 than some other colorectal lines, which may explain the high dose of Inhibitor-4 (200 μM) needed to reduce the cell viability and proliferation levels by 30 and 50 percent, respectively." (PMID 35076487, 2021). "Upregulation of MLL1 and SMYD3 increases H3K4 methylation, as well as induces breast and colorectal cancer, fibrosarcoma, and HCC." (PMID 27183310, 2016).
prostate carcinoma (24 papers, 2009 to 2025). A carcinoma that arises from epithelial cells of the prostate gland. "While further investigation into the function of SMYD3 in prostate cancer is necessary, SMYD3 overexpression was associated with worse disease-specific survival in a cohort of 189 prostate cancer patients independently of other known prognostic factors." (PMID 33050946, 2020). "A SMYD3 inhibitor named BCI-121 with anti-proliferative effects on tumor cell lines including prostate cancer models has been described, and its activity was linked to SMYD3 levels." (PMID 28486411, 2017). "In general, SMYD3 expression is very weak or undetectable in the majority of normal human tissues, whereas its overexpression has been implicated in the development and progression of colorectal, hepatocellular and prostate cancer." (PMID 32007952, 2020). "Furthermore, SMYD3 is significantly associated with the proliferation, invasion, cell cycle regulation, prognosis, and recurrence of malignant tumors, such as liver, breast, and prostate cancers." (PMID 36816359, 2023). "Primary prostate carcinoma expression profiles also demonstrated SMYD3 overexpression and CCND2 downregulation." (PMID 33637115, 2021). "In summary, SMYD3 is commonly overexpressed in prostate cancer and is an independent predictor of poor outcome." (PMID 33637115, 2021). "For instance, SMYD3 directly targets the androgen receptor and telomerase gene, thereby promoting development and progression of prostate cancer and other human malignancies." (PMID 32007952, 2020). "Clinicopathologic associations of SMYD3, which is known to methylate H3K4 and H4K20, have been investigated in HCC and prostate cancer." (PMID 33050946, 2020). "Androgen receptor (AR) signaling is known to be involved in the etiology and progression of BC, while the AR gene is a direct target of SMYD3 in prostate cancer." (PMID 32007952, 2020). "In prostate cancer, SMYD3 elicits its oncogenic activity by stimulating androgen receptor (AR) transcription." (PMID 31935919, 2020). "An elevated expression is predictive of prostate cancer aggressiveness and selective SMYD3 gene silencing reduces tumor growth in vitro and in vivo." (PMID 28486411, 2017). "Knockdown of SMYD3 caused differentially expressed DNA repair genes RAD50 and RAD51 in prostate cancer cells." (PMID 28630472, 2017). "In the present study, we found high expression of SMYD3 in the prostate cancer cell line LNCaP and weaker expression in prostate cancer PC3 cells." (PMID 23285160, 2012). "Preliminary results show that SMYD3 is highly expressed in prostate cancer tissues and plays an important role for the growth and survival of prostate cancer cells (manuscript in preparation)." (PMID 23285160, 2012). "These SMYD3-mediated methylation events have been observed in prostate cancer cell lines and in in vitro assays using histones from HeLa cells; however, H4K20me3 was not shown to be a substrate of SMYD3 in other cell line tested, including MEFs, HeLa, and MCF7 cells." (PMID 37671044, 2023). "Furthermore, the authors analyzed global methylation levels of various histone marks and found H4K20me3 predominantly affected by SMYD3 depletion in prostate cancer cell lines." (PMID 33637115, 2021). "They then focused on mechanisms whereby SMYD3 carries out its oncogenic effects in prostate cancer." (PMID 33637115, 2021). "SMYD3 is also highly expressed in prostate cancer, E2F-1 could exert its IGF-1R transactivation effect through both direct and indirect pathways." (PMID 32007952, 2020). "In addition, we observed strong SMYD3 expression in the prostate cancer cell line LNCaP and its inhibition led to decreased 15-LOX-1 expression." (PMID 23285160, 2012). "Since 15-LOX-1 has been suggested to play an important role in tumorigenesis and metastasis of prostate cancer, further investigation of the relation between SMYD3 expression and 15-LOX-1 transcriptional activation in prostate cancer in vitro and in vivo should be informative." (PMID 23285160, 2012).
prostate carcinoma (continued). "Since 15-LOX-1 upregulation is suggested to be involved in the tumorigenesis of prostate cancer, it was also examined whether SMYD3 is required for 15-LOX-1 transcription in the prostate cancer cell line LNCaP." (PMID 23285160, 2012). "It was very interesting to identify EZH2 and SMYD3 as the most significantly changed and overexpressed histone modifiers in prostate cancer, since the two modifications are antagonistic and correspond to repressive (H3K27me3) and active (H3K4me3) gene transcription, respectively." (PMID 19262738, 2009). "While no changes in H3K4 and H3K27 methylation marks were seen, there was a significant decrease in the H4K20me3 repressive mark in sh-SMYD3 prostate cancer cells, providing further evidence that SMYD3 expression may repress CCND2 expression via H4K20 tri-methylation in prostate cancer." (PMID 33637115, 2021). "Additionally, the authors identified that SMYD3-depleted prostate cancer cells show S phase arrest, and this correlates with increased expression of cyclin D2 (CCND2), a key cell cycle regulator at the G1/S checkpoint that has been shown to be frequently silenced in prostate carcinomas." (PMID 33637115, 2021). "These preliminary results provide evidence that SMYD3 may be a rational target for prostate cancer." (PMID 33637115, 2021). "It was reported that the suppression of SMYD3 could attenuated malignant phenotype of prostate cancer either by deleting the SET function domain or silencing SMYD3, indicating the function of SMYD3 on tumor growth might associated with histone methyltransferase activity." (PMID 29029425, 2017). "One report showed that SMYD3 depletion reduced H4K20me3 level to upregulate CCND2 expression, whose restoration attenuated the hyperproliferative phenotype in prostate cancer LNCaP cells." (PMID 37386026, 2023). "The authors found that SMYD3, Ki67, and EZH2 independently predicted prostate cancer patient outcome adjusted for standard clinicopathologic parameters in their cohort." (PMID 33637115, 2021). "SMYD3 targets Cyclin D2 through H4K20 trimethylation and contributes to a more aggressive phenotype of prostate cancer." (PMID 28050603, 2017). "We found that the most significantly changed epigenetic regulators in both prostate cancer tissues and cell lines were EZH2, SMYD3 and DNMT3A, which function as H3K27 trimethyltransferase, H3K4 di/tri-methyltransferase and DNA methyltransferase, respectively." (PMID 19262738, 2009). "Similarly, SET and MYND domain-containing protein 3 (SMYD3) has also been identified as an upregulated H3 and H4 lysine methyltransferase promoting cell proliferation and migration, thus emerging as a predictive marker of prostate cancer." (PMID 29888169, 2018).
colon carcinoma (17 papers, 2015 to 2025). "There was a significant reduction of E-cadherin staining intensity in the liver/colon tumors of wild-type mice as compared to Smyd3-deficient mice." (PMID 33637115, 2021). "Using affinity purification and mass spectrometric approaches, we purified proteins that stably associate with SMYD3 from colon cancer cells and identified PC4 as one of the associated factors." (PMID 26350217, 2015). "When the mice were exposed to DEN/DMH/DSS treatments that induce liver or colon cancer, there was a dramatic reduction in gross tumor size and number in the Smyd3-deficient group with only a few focal nodular hyperplastic areas detected histologically in the DEN-treated Smyd3-deficient mice." (PMID 33637115, 2021). "Furthermore, mRNA levels of transcription regulators (Snai1, Snai2, Twist, Zeb1, and SOX4) and EMT marker genes (Fn1, Vimentin, Timp1, Mmp2, Mmp7, Mmp9, Mmp14) were significantly increased in liver/colon tumors of wild-type mice when compared to Smyd3-deficient mice." (PMID 33637115, 2021). "In both liver and colon tumors, SMYD3 interacts with RNA pol II to promote the transcription of genes involved in cell proliferation and metastasis." (PMID 35406445, 2022). "In colon cancer and hepatocarcinoma cell lines, SMYD3 forms transcription complexes with HSP90 and RNA polymerase II to promote H3K4 methylation and regulate the transcription of the target gene NK2homeobox8 (Nkx28), promoting tumor cell proliferation." (PMID 34335697, 2021). "In liver cancer and colon cancer, SMYD3 is localized in the cell nucleus and selectively promotes oncogene expression via interplay with histones." (PMID 31417652, 2019). "The phosphorylation level of AKT1 at Thr 308 was significantly diminished after knockdown of SMYD3 in the human colon cancer SW480 cells." (PMID 27626683, 2016). "MTT assays over a period of 4 days reproducibly showed that the bladder and colon cancer cells proliferate much more slowly following the depletion of endogenous SMYD3." (PMID 26350217, 2015). "Overall, our microarray and ChIP data establish the role for SMYD3 in regulating particular sets of genes in bladder and colon cancer cells." (PMID 26350217, 2015). "To check this possibility, we generated HCT116 colon cancer cell lines stably expressing SMYD3 fused to FLAG and HA epitope tags." (PMID 26350217, 2015). "The observed overexpression of SMYD3 in bladder and colon cancer cell lines encourages the possibility that SMYD3 may facilitate key tumorigenic processes such as cell proliferation and invasion." (PMID 26350217, 2015). "For example, SMYD3‐mediated AKT methylation at lysine 14 plays pivotal roles in activation of the AKT signaling pathway in breast and colon cancers, and PRMT1‐mediated methylation at arginine 887 of INCENP promotes mitosis of lung and cervical cancers." (PMID 28370702, 2017). "The observed interaction between SMYD3 and PC4 raised the possibility that SMYD3 functionally cooperates with PC4 to establish the active state of target genes in bladder and colon cancer cells." (PMID 26350217, 2015). "Our data show that SMYD3 colocalizes with PC4 at genes regulating cell proliferation and invasion and establishes transcriptional competence in bladder and colon cancer cells." (PMID 26350217, 2015). "In summary, we have demonstrated that SMYD3 promotes cell proliferation and invasion by mediating H3K4me3 and PC4 recruitment at the proximal promoter and coding regions of target genes, thereby positively influencing their expression in bladder and colon cancer cells." (PMID 26350217, 2015).